ALB (albumin)
Diseases named in the same sentence as ALB in open-access papers (continued):
Sharing a sentence is not in itself a finding about the gene and the disease.
gastric cancer (continued). "A study conducted in 793 patients with gastric cancer found TNM stage, operative morbidity, serum albumin, age, type of lymphadenectomy and gastrectomy performed to be independent prognostic factors." (PMID 21176210, 2010). "A study in patients with gastric cancer showed that worse performance status, high albumin levels, no implantation procedure, and implantation not performed by specialized groups were risk factors for PORT complications." (PMID 41044703, 2025). "CRP-to-albumin ratio (CAR), a biomarker related to inflammation and nutrition, has been demonstrated as a prognostic factor in various cancers including colorectal cancer, gastric cancer, pancreatic cancer, esophageal cancer, and ovarian cancer." (PMID 40416620, 2025). "The Japanese phase 3 ABSOLUTE trial revealed that the median overall survival (OS) with albumin-bound paclitaxel was non-inferior to solvent-based paclitaxel, leading to its approval in Japan for the second-line treatment of advanced gastric cancer." (PMID 41550955, 2025). "Albumin (ALB), B-cell lymphoma 2 (BCL-2), nuclear factor kappa B subunit 1 (NFKB1), hypoxia-inducible factor 1 alpha (HIF1A), and interleukin 6 (IL-6) had a higher expression in gastric cancer than in normal conditions." (PMID 39816318, 2024). "In addition to previous studies, we observed that the CRP/albumin and CEA/albumin ratios can be used to track the efficacy of treatment and predict the pathological response of patients experiencing gastric cancer." (PMID 38792528, 2024). "According to the results of this study, CEA/albumin and CRP/Albumin ratios may be important in predicting pathological response in patients with locally advanced gastric cancer receiving neoadjuvant therapy and surgery." (PMID 38792528, 2024). "This article will compare the effects of Nab-PTX, 5-Fu, LBP, and albumin paclitaxel + 5-pentafluorouracil (Nab-PTX + 5-Fu) on AGS cells from the perspective of autophagy and apoptosis, which is to provide new ideas and experimental evidence for gastric cancer." (PMID 35719323, 2022). "In fact, serum albumin, total lymphocyte count, and total cholesterol, which are components of GNRI and CONUT, were weakly correlated with skeletal muscle index in patients with gastric cancer." (PMID 35224261, 2022). "Parameters such as serum albumin, prealbumin (PA), body mass index (BMI), skeletal muscle mass (SMA), and prognostic nutritional index (PNI) are predictive indicators for both prognosis and postoperative complications in patients with gastric cancer." (PMID 35433809, 2022). "For example, Japanese researchers applied albumin combined with paclitaxel nanoparticles to carry out a phase III clinical study on 741 patients with advanced gastric cancer who were not sensitive to first-line chemotherapy." (PMID 34276374, 2021). "Other factors including age, sex, BMI, location of gastric cancer, location of gastric cancer, treatment regimen for gastric cancer, visceral adiposity, fatty liver, serum albumin level, and blood HbA1c level were not selected by a stepwise variable selection." (PMID 32599747, 2020). "Based on multivariate logistic regression analysis, suspected gastric wall thickness increase, age, and Hb values were independent variables in the diagnosis of gastric cancer (p < 0.05) while albumin was not significant (p > 0.05)." (PMID 31827513, 2019). "The prognosis of patients with gastric cancer is poor, especially in patients with metastatic lymph nodes and low serum albumin levels, who are considered not suitable for surgical treatment." (PMID 25523120, 2014). "In addition, patients who developed DGE following gastric cancer surgery also had significantly lower serum albumin levels than those without DGE." (PMID 40988445, 2025). "Whether adjuvant nanoparticle albumin-bound paclitaxel (nab-paclitaxel) combined chemotherapy is more effective than the XELOX standard adjuvant chemotherapy in patients with stage III gastric cancer has not been confirmed." (PMID 33435909, 2021).
gastric cancer (continued). "However, the change in NRI between before and 1 year after surgery (dNRI) did not influence the overall survival in gastric cancer patients and the level of albumin was higher at postoperative 1 year compared to preoperative value." (PMID 33579228, 2021). "On the other hand, the same study group could recently show, that CRP, but not albumin is an independent prognostic factor in gastric cancer patients." (PMID 29467943, 2018). "Although they might improve prognostic predictions in gastric cancer, no measurements or indices that combine serum bilirubin and albumin levels have been developed." (PMID 28476041, 2017). "We observed that after adjustments according to the albumin levels, the lysophosphatidylserine (LysoPS) and lysophosphatidylglycerol (LysoPG) levels were significantly higher, while the LysoPA and ATX levels were lower, in the ascites from patients with gastric cancer." (PMID 28143894, 2017). "Additionally, the hemoglobin, albumin, lymphocyte, and platelet (HALP) score is a promising indicator of both nutritional and inflammatory status, and its prognostic value has recently been confirmed in hepatocellular carcinoma, gastric cancer, colorectal cancer, and small cell lung cancer." (PMID 37809958, 2023). "Notably, both albumin (Alb) ≥ 40 g/l and lymphocyte-to-monocyte ratio (LMR) ≥ 3.4 were found to be protective factors for gastric cancer (GC), indicating that inflammation is relatively beneficial under certain situations for tumour prognosis." (PMID 35285399, 2022). "Contrary to the higher levels of LysoPS in ascites from gastric cancer group, we did not observe any difference in the PS-PLA1 levels between the two groups either with or without adjustments to the ALB." (PMID 28143894, 2017). "Comparing patients with metastatic and nonmetastatic gastric cancer, it was found that they were different statistically according to prealbumin and CRP and not albumin." (PMID 26904109, 2016).
pancreatic cancer (212 papers, 2009 to 2026). "Low albumin levels were associated with high-risk mortality in patients with upper gastrointestinal cancer, hepatobiliary and pancreatic cancer, and colorectal cancer." (PMID 38438901, 2024). "In summary, nutritional risk, as measured using weight and albumin is significantly associated with survival among patients with pancreatic cancer." (PMID 36145174, 2022). "Hospitalization days ≥7 days, number of admissions ≥2 times, surgery, chemotherapy, the type of antibiotics used ≥2 species, albumin<40.0 g/L, and prealbumin < 0.2 g/L were the potential risk factors for pancreatic cancer patients with E. coli BSI (P < 0.1)." (PMID 35340919, 2022). "In our analysis, albumin <40.0 g/L and prealbumin <0.2 g/L were the potential risk factors, indicating that patients with pancreatic cancer were prone to E. coli BSI when their nutritional status is low." (PMID 35340919, 2022). "The lower serum ALB levels can increase the risk of venous thromboembolism, which is the second leading cause of death in pancreatic cancer patients." (PMID 32197468, 2020). "Other common serum markers of inflammation such as haptoglobin, leukocytes and albumin, are less well studied in relation to the risk of pancreatic cancer even though they have been found to be associated with other malignancies." (PMID 31464604, 2019). "The median serum albumin levels were slightly lower, while the carbohydrate antigen 19-9 levels, pancreatic cancer-associated antigen levels, and s-pancreas-1 antigen levels were higher, than their normal ranges." (PMID 30218151, 2018). "Furthermore, albumin and albumin-related drugs accumulate in KRAS-mutated pancreatic cancer cells and tissues." (PMID 39070787, 2024). "Oxaliplatin, irinotecan, fluorouracil, and leucovorin combination (FOLFIRINOX) and gemcitabine plus albumin-bound paclitaxel (GEM+NPTX) had better outcomes associated with reduced risk of death as primary chemotherapy for pancreatic cancer than the unapproved drugs in Japan." (PMID 35099549, 2022). "In this study, adjusting for hypo-nutrition by measuring serum albumin level showed that appetite loss could affect the mortality of patients with unresectable pancreatic cancer." (PMID 36554049, 2022). "As unintentional weight loss, systemic inflammation and poor nutritional status are hallmarks of cachexia and are prevalent in this disease, monitoring weight, nutritional risk and albumin are critical in the care of patients with pancreatic cancer to halt cachexia development and progression." (PMID 36145174, 2022). "Furthermore, albumin, an endogenous antioxidant, recognized as a risk factor for poor prognosis in pancreatic cancer, in our series was found to be normal in cases of tumor localized in the body or tail of the pancreas." (PMID 34123859, 2021). "In this study, we evaluated associations between standard pre-diagnostic serum markers of chronic inflammation (CRP, albumin, haptoglobin and leukocytes) and pancreatic cancer risk in the Swedish Apolipoprotein-related MORtality RISk (AMORIS) prospective cohort study." (PMID 31464604, 2019). "The current study aimed to evaluate associations between standard pre-diagnostic serum markers of chronic inflammation (CRP, albumin, haptoglobin and leukocytes) and pancreatic cancer risk in the prospective Swedish Apolipoprotein-related MORtality RISk (AMORIS) cohort study." (PMID 31464604, 2019). "Low level of ALB has been found to be a solid risk factor for poor prognosis of pancreatic cancer." (PMID 30474926, 2018). "Preliminary results in head and neck and pancreatic cancer have suggested that high SPARC expression could be also associated with response to albumin-bound paclitaxel." (PMID 23638089, 2013). "Therefore, the combination of low cholesterol, low serum albumin, and low lymphocyte counts may be associated with poor survival of pancreatic cancer patients and low CONUT scores." (PMID 37568634, 2023).
pancreatic cancer (continued). "This study evaluated how triceps skinfold thickness, reflecting body fat, and serum albumin levels, indicating nutritional status, relate to overall survival in patients with pancreatic cancer receiving chemotherapy." (PMID 41907431, 2026). "We prospectively evaluated 353 patients with pancreatic cancer, repeatedly measuring triceps skinfold thickness and serum albumin from baseline through follow-up." (PMID 41907431, 2026). "Especially in pancreatic cancer, the combination of gemcitabine and albumin bound paclitaxel has become one of the first-line standard protocols." (PMID 41293424, 2025). "Lean body mass was reported to increase significantly in patients receiving jejunal feeding during chemotherapy for pancreatic cancer, and albumin levels remained stable during enteral feeding." (PMID 40009216, 2025). "The t-AUC analysis confirmed that the A-SII score outperformed albumin or SII alone in predicting the prognosis of advanced pancreatic carcinoma." (PMID 40265018, 2025). "The study aims to establish a nomogram to predict advanced pancreatic carcinoma patients’ overall survival (OS), incorporating albumin combined with systemic immune-inflammation index (A-SII) score and clinical characteristics." (PMID 40265018, 2025). "This study is the first to investigate the prognostic value of albumin combined with SII in patients with advanced pancreatic carcinoma." (PMID 40265018, 2025). "Albumin-conjugated nanocarriers of Paclitaxel have improved the efficacy of the first-line pancreatic cancer drug Gemcitabine by inhibiting the tumor stroma and suppressing the expression of the gemcitabine-inactivating enzyme cytidine deaminase." (PMID 38375157, 2024). "We present a compelling strategy for the treatment of advanced pancreatic cancer using innovative albumin-based NPs (BCP NPs) and a biodegradable PLGA-PEG-PLGA hydrogel system." (PMID 39770508, 2024). "As of now, FOLFIRINOX or gemcitabine in combination with albumin-bound paclitaxel represents the mainstream chemotherapy for advanced/metastatic pancreatic cancer." (PMID 38378604, 2024). "The Food and Drug Administration (FDA) has approved albumin-bound paclitaxel (nab-PTX) NPs as a primary treatment for advanced pancreatic cancer, and nab-PTX NPs show high treatment efficacy." (PMID 39770508, 2024). "Our findings specifically support the integration of PS and albumin assessments into routine clinical practice in pancreatic cancer as simple, accessible tools for guiding EoL decisions." (PMID 39330032, 2024). "Our study presents a novel approach to addressing the challenges in pancreatic cancer treatment by combining albumin-based nanoparticles (BCP) with a thermosensitive PLGA-PEG-PLGA hydrogel for localized drug delivery." (PMID 39770508, 2024). "APAR, consisting of ALP and ALB, was previously reported as a predictive biomarker in patients with pancreatic cancer and HCC." (PMID 38834790, 2024). "substantiated the CRP/albumin ratio’s role as a tool for predicting survival rates and gauging the effectiveness of chemotherapy in advanced pancreatic carcinoma." (PMID 38496751, 2024). "There is substantial evidence that albumin-bound paclitaxel (nab-paclitaxel) is effective and safe for the treatment of breast, lung and pancreatic cancers." (PMID 37270638, 2023). "dFdC, either alone or in combination with paclitaxel albumin-bound particles (Abraxane), is used as a frontline regimen for pancreatic cancer chemotherapy; however, its limited benefits on treatment and survival outcomes are of significant concern." (PMID 37264059, 2023). "CRP/albumin ratio is used as a prognostic mediator for several cancers such as hepatocellular lung cancer, newly diagnosed pancreatic cancer, renal cancer or ovarian cancer." (PMID 37465171, 2023). "In pancreatic cancer, the albumin level of COPZ1 was lower in tumor tissue when compared to normal tissue." (PMID 37107648, 2023).
pancreatic cancer (continued). "SOX8 transcriptionally regulated EZH2, which reduced expression of SPARC by promoting the methylation of SPARC, thereby reducing the transport of albumin-bound paclitaxel in pancreatic cancer cells." (PMID 35173526, 2022). "According to National Comprehensive Cancer Network Guidelines (ver 2.2021), chemotherapy with FOLFIRINOX and GEM with albumin-bound paclitaxel (GEM/nab-PTX) were mainly recommended as systemic therapy for advanced pancreatic cancer." (PMID 35544539, 2022). "Albumin-conjugated doxorubicin’s efficacy has been shown to be FcRn-sensitive in pancreatic cancers." (PMID 35806069, 2022). "FOLFIRINOX and gemcitabine plus nanoparticle albumin-bound(nab) paclitaxel are common first-line therapies for advanced pancreatic cancer." (PMID 36612289, 2022). "Since nab-paclitaxel was recommended as the first-line treatment option for advanced pancreatic cancer, the synthesis of albumin nanoparticles has attracted rising attention from reserchers." (PMID 35656085, 2022). "In our previous research, we used human serum albumin as a carrier of gemcitabine, synthesized gemcitabine albumin nanoparticle by nano-binding technology, and verified its improved antitumor effect on pancreatic cancer." (PMID 35656085, 2022). "Based on this fact, numerous attempts have been made to investigate the therapeutic potential of paclitaxel-loaded albumin-encapsulated liposomes against intractable pancreatic cancer in tumor-bearing mice." (PMID 33810483, 2021). "Further, gemcitabine, a first-line therapy for pancreatic cancer, has been also successfully loaded in human serum albumin NPs and showed strong inhibitory effect on tumour growth against the pancreatic tumour cell line BxPC-3 both in vitro and in vivo." (PMID 35582007, 2021). "Combination therapy with gemcitabine and nanoparticle albumin-bound paclitaxel (nab-paclitaxel), known as GnP therapy, significantly prolongs the survival of pancreatic cancer patients compared with gemcitabine monotherapy." (PMID 34260659, 2021). "In pancreatic cancers, breakdown of albumin through lysosomal hydrolases has been posited as a major nutrient source and that MTORC1-TFEB signaling is increased specifically by acid-selective accumulation of lysosomotrophic drugs, leading to resistance." (PMID 32515674, 2021). "Low albumin level was described as a good indicator to predict outcomes in pancreatic cancer and intraoperative complications in pancreatic surgery, which is an important parameter when assessing the general clinical condition of the patients." (PMID 34898583, 2021). "In case 2, a 70-year-old Japanese man, who received nanoparticle albumin-bound paclitaxel for pancreatic cancer with multiple metastases, developed bilateral cystoid macular edema." (PMID 34284818, 2021). "(2016) described albumin NPs decorated with cyclic arginine-glycine-aspartic (cRGD) peptides loaded with gemcitabine for the treatment of pancreatic cancer." (PMID 31858848, 2020). "The acquisition of these amino acids from extracellular albumin is inhibited by EIP-amiloride, suggesting that macropinocytosis is used by pancreatic cancer cells to scavenge extracellular proteins such as albumin to fuel proliferation." (PMID 32756454, 2020). "The PTX/CCM albumin NPs demonstrated in vitro anti-tumor efficacy against pancreatic cancer cells (Mia Paca-2 cells)." (PMID 31858848, 2020). "Recently, the neutrophil-albumin ratio has been identified as a prognostic predictor in patients with rectal cancer and palliative pancreatic cancer." (PMID 32238212, 2020). "Previous studies focused on the neutrophil-to-albumin ratio, mainly in significantly predicting prognosis of palliative pancreatic cancer treatment and rectal cancer." (PMID 32238212, 2020). "A small study at the Royal Infirmary of Edinburgh, including 42 pancreatic cancer patients and 12 controls, observed a statistically significant lower serum albumin levels in pancreatic cancer patients compared to controls." (PMID 31464604, 2019).